PPARA (peroxisome proliferator activated receptor alpha)
Diseases named in the same sentence as PPARA in open-access papers (continued):
Sharing a sentence is not in itself a finding about the gene and the disease.
neurodegenerative disease (37 papers, 2013 to 2025). A disorder of the central nervous system characterized by gradual and progressive loss of neural tissue and neurologic function. "Studies from our lab have demonstrated that peroxisome proliferator-activated receptor α (PPARα) acts as an important regulator of many neurodegenerative diseases and that CA binds to the ligand-binding domain of PPARα." (PMID 38532783, 2024). "Previous reports from our group have shown PPARα to act as a master regulator for many neurodegenerative diseases." (PMID 38132111, 2023). "The interest for the possible role of PPARα in neurodegenerative diseases stems from the well-known range of effects elicited by PPARα in the nervous system and outside the nervous system." (PMID 35625650, 2022). "As for PPARα, it has been found that downregulation can affect antioxidant and anti-inflammatory responses in other degenerative diseases such as AD." (PMID 35463999, 2022). "Conversely, limited data are available on the involvement of PPARα in other neurodegenerative diseases." (PMID 35625650, 2022). "The nuclear receptors (NRs) RARα, RXRα, PPARα, and PPARγ represent promising pharmacological targets for the treatment of neurodegenerative diseases." (PMID 30759808, 2019). "Overall, these observations suggest that PPARα may be a promising target for the treatment of neurodegenerative diseases characterized by increased inflammatory processes." (PMID 35625650, 2022). "Cinnamic acid may also be considered a good candidate to prevent neurodegenerative diseases by reducing cerebral amyloid–beta plaque burden by activating the nuclear hormone receptor PPARα." (PMID 35883842, 2022). "Recently, it has also been shown that the stimulation of RARα, RXRα, and PPARα/γ may be beneficial in treating neurodegenerative diseases." (PMID 30759808, 2019). "However, oxidative stress and inflammation play prominent roles in many neurodegenerative diseases, and experimental evidence suggests that PPARα's antioxidant and anti-inflammatory properties may be responsible in part for its neuroprotective effects." (PMID 25705219, 2015). "However, PPARα's beneficial effects in endothelial survival and function may also play a role in PPARα-mediated neuroprotection, as vascular dysfunction contributes to many neurodegenerative diseases." (PMID 25705219, 2015).
liver (20 papers, 2011 to 2025). "As such, allopurinol could improve fatty liver through the modulation of PPARα signaling, and its efficacy serves as evidence that uric acid is directly involved in the development of NAFLD." (PMID 33972568, 2021). "The activation of the peroxisome proliferator-activated receptor alpha (PPAR-α) pathway due to increased fatty acid availability further exacerbates these effects, impairing CD4+ T-cell function and promoting liver carcinogenesis." (PMID 39000296, 2024). "Moreover, we previously showed that OEA pre-treatment reduced infarct volume from middle cerebral artery occlusion in wild-type, but not in PPARα-null, mice." (PMID 22584002, 2012).
cardiac diseases (18 papers, 2005 to 2026). "The promoter region of CD36 contains PPARα response elements, and its expression levels during cardiac disease have been associated with levels of PPARα and PGC1α expression." (PMID 35050131, 2021). "Common variants of the PPARA gene have been found to associate with ischaemic heart disease in non diabetic men." (PMID 16309557, 2005). "PPARα transcriptional activity depends on endogenous (e.g., fatty acids) and exogenous ligands (e.g., fibrates), making synthetic PPARα agonists promising therapeutic agents in cardiac disease." (PMID 41496209, 2026). "For this reason, agonists that modulate the activity of PPARa and PPARg have been considered for the treatment of cardiac diseases." (PMID 41511296, 2025). "PPARα is a key transcriptional regulator of fatty acid metabolism and plays a role in the development of heart disease." (PMID 35259201, 2022). "In this review, we summarize and discuss the role of PPARs, particularly PPARα, in the healthy heart and cardiac diseases." (PMID 30400386, 2018). "These context-dependent effects highlight a complex role of PPARα in cardiac diseases." (PMID 42193950, 2026). "Much of our understanding of the roles of the PPAR isoforms, PPARα, PPARδ and PPARγ are in metabolic regulation, as they play roles in insulin sensitivity, glucose homeostasis and oxidation of fatty acids and cardiac disease." (PMID 40704293, 2025).
bacterial infection (17 papers, 2010 to 2025). "Animal experiments indicate that deficiency in peroxisome proliferator-activated receptor alpha (PPARα) impairs ketogenesis activation, which is associated with increased mortality in mice following bacterial infection." (PMID 40416376, 2025). "CYP450 metabolites reduced the protective inflammatory responses via PPARα activation, thereby increasing the susceptibility to secondary bacterial infection following IAV infection." (PMID 36831317, 2023). "Deficiency in hepatic PPARα causes an impaired metabolic response, and upon bacterial infection, PPARα-null mice have a higher mortality rate." (PMID 32708786, 2020). "The molecular mechanisms by which PPARα/γ mediates immune modulation during a bacterial infection following IAV infection require urgent attention." (PMID 36831317, 2023). "However, during superinfection, the pathological production of DHET excessively activates PPARα, compromising the immune system’s ability to control secondary bacterial infections." (PMID 35860381, 2022). "On the other hand, PPARα activation has been shown to be protective against bacterial infections." (PMID 35003101, 2021).
neurological diseases (17 papers, 2013 to 2025). "PPARα is a transcription factor with neuroprotective effects reported in various neurological disease models, including AD and PD." (PMID 36422287, 2022). "PPARα is known to be modulated in neurologic disease, including AD, and several studies emphasize the possible treatment of AD based on PPARα natural or synthetic ligands." (PMID 33239403, 2021). "Together, these findings support the notion that PPARα activation is a promising therapeutics for neurologic disease and CNS injury." (PMID 34586065, 2021).
retinopathy (13 papers, 2013 to 2025). "Furthermore, PPARα-deficient (Pparα−/−) mice exposed to oxygen-induced retinopathy (OIR) demonstrated detrimental consequences, including heightened retinal cell death and intensified glial activation, in contrast to wild-type OIR mice." (PMID 38004166, 2023). "Together with assessing microglial metabolism under diabetic stress in the presence and absence of Pparα expression, we have provided insight into the role of microglial PPARα in retinopathy under diabetic conditions." (PMID 36497130, 2022). "Previous studies from our laboratory have reported beneficial roles of PPARα in retinopathy and provided some insight into its mechanisms of action." (PMID 36497130, 2022). "To verify the effect of PPARα in IR-induced retinopathy, we used a specific PPARα agonist, FA, to activate PPARα and ascertain if PPARα plays an important part in this pathologic process." (PMID 35004756, 2021). "In this paper, we reveal a therapeutic effect of a selective PPARα modulator (SPPARMα), pemafibrate, against pathological angiogenesis in murine models of retinopathy." (PMID 31771164, 2019). "All these results suggest that PPARα activation had a protective role in the retina, and PPARα itself could be a potential target for treatment of IR-induced retinopathy." (PMID 35004756, 2021). "In particular, we emphasized that PPARα agonists could possess the potential to protect against DR and described SPPARMα (pemafibrate) with its potential effects for various retinopathies, including DR." (PMID 33086679, 2020). "We and others have demonstrated that PPARα has neuroprotective effects in retinopathy and that this protective effect may be due to alleviation of oxidative stress and inflammation." (PMID 25705219, 2015). "Because PPARα has a therapeutic effect in DR and is neuroprotective in several disease models, it is reasonable to hypothesize that PPARα may be neuroprotective in retinopathy, which is characterized in part by neurodegeneration." (PMID 25705219, 2015). "Pharmacological PPARα activation by palmitoylethanolamide (PEA) reduced retinal neovascularization and fibrotic changes and suppressed glial activation in proliferative retinopathy and neovascular age-related macular degeneration mouse models." (PMID 33086679, 2020). "Our findings suggested that PPARα decreased expression of vascular endothelial growth factor (VEGF) and its receptors, potentially by deactivating pathological Wnt signaling in retinopathy." (PMID 25705219, 2015). "A recent report also demonstrated that fenofibrate reduced the severity of retinopathy in db/db mice (another mouse model of DR) without inducing PPARα-dependent gene expressions in the retina." (PMID 34833044, 2021). "One prior study identified that fenofibrate was neuroprotective in retinopathy of type 2 diabetes, but did not determine whether these effects were related to PPARα activation or evaluate the molecular mechanism of action." (PMID 30716067, 2019). "In PPARα knockout mice, fenofibric acid treatment could not reduce upregulated expression of HIF-1α in the ischemic retina of oxygen-induced retinopathy." (PMID 33799938, 2021).
inflammation (11 papers, 2005 to 2025). Aberrant reaction of the microcirculation characterized by movement of fluid and leukocytes from the blood into extravascular tissues. "We have here investigated the role of PPARα in a mouse model of LPS-induced airway inflammation characterized by cell infiltration, production of chemoattractants and increased MMP activity." (PMID 16091136, 2005). "Several studies have shown that peroxisome proliferator-activated receptor α (PPARα) agonist could inhibit renal inflammation and fibrosis and prevent renal oxidative stress." (PMID 32446306, 2020). "Therefore, the protective role of PPARα induction against liver inflammation and fibrosis was mediated by up-regulating anti-inflammatory and anti-fibrogenic cytokines." (PMID 23388073, 2013).
immune dysfunction (10 papers, 2016 to 2025). "Genetic depletion or pharmacologic inhibition of PPARα effectively attenuates TDE-induced DC-based immune dysfunction and enhances the efficacy of immunotherapy." (PMID 33086073, 2020). "While these pathways are not typically associated with liver function, it suggests that 10-HSA activated PPARα signaling may promote both innate and adaptive immune processes and overcome effects of the AFB1 exposure on immune dysfunction." (PMID 40793786, 2025).
psychiatric diseases (10 papers, 2019 to 2024). "Currently, multiple PPARα natural and synthetic agonists are being tested in clinical studies or experimental models of neurodegenerative/psychiatric diseases." (PMID 38023298, 2023). "PPARα is altered in multiple kinds of neurodegenerative/neurodevelopmental and psychiatric disorders, suggesting that this receptor could be a viable target in novel therapeutic strategies." (PMID 38023298, 2023).
myopathy (9 papers, 2010 to 2025). A disease of the muscle in which the muscle fibers do not function properly. "Some studies reported that PPARα activation in skeletal muscle transactivated the genes encoding muscle proteases, and the increased expression of skeletal muscle proteases led to severe myopathy." (PMID 32028670, 2020). "Analyzing the relationship between fenofibric acid and myopathy from its target perspective, one of its primary targets, peroxisome proliferator-activated receptors (PPARs), consists of three subtypes: PPARα, PPAR-β/δ, and PPAR-γ." (PMID 41282005, 2025). "Based on these functions, PPARα does not seem to be directly associated with myopathy and may even have a protective role." (PMID 41282005, 2025). "In humans and mice, a negative side effect of PPARα activation in muscle is in rare cases (<1%) muscle weakness and pain (myopathy) or very seldom breakdown of muscle (rhabdomyolysis)." (PMID 20847941, 2010).
infectious disease (6 papers, 2016 to 2025). A disorder directly resulting from the presence and activity of a microbial, viral, or parasitic agent in humans. "Thus, the roles of PPARα in infectious diseases should be studied in wide ranging aspects, including metabolism and inflammation." (PMID 36831317, 2023).
heart (4 papers, 2015 to 2025). "Because, especially PPARα activation has been shown to be cardio-protective in the hypertrophic heart, de-activation of this transcription factor may further worsen the metabolic and energetic state of the hypertrophic heart." (PMID 29930945, 2018).
peripheral neuropathy (4 papers, 2013 to 2025). A disorder affecting the peripheral nervous system. "We previously demonstrated that A190, a novel, potent, and selective PPARα agonist, effectively alleviates chemotherapy-induced peripheral neuropathy and CFA-induced inflammatory pain as a non-opioid therapeutic agent." (PMID 40867546, 2025).
brain diseases (3 papers, 2018 to 2021). "Taken together, reports on the therapeutic roles of PPARα activation in various brain diseases are growing in number." (PMID 34833044, 2021).
intestinal disorder (3 papers, 2022 to 2024). A non-neoplastic or neoplastic disorder that affects the small or large intestine. "PPARα and PPARγ ligands are promising therapeutic tools for immune-mediated intestinal diseases based on their anti-inflammatory and antifibrotic activity." (PMID 39451206, 2024).
respiratory diseases (1 paper, 2025). "The “active component–target–disease” network further demonstrated these essential oil components’ potential efficacy against pain, tumors, neuropsychiatric diseases, eye diseases, and respiratory diseases, which were highly related to PPARA, GABRA1, PTGS2, and SLC6A2." (PMID 40729010, 2025).
PPARA also shares sentences with these, for which no sentence is quoted: systemic lupus erythematosus (35 papers); staphylococcus aureus infection (33); primary immunodeficiency (30); malaria (25); amoebiasis (20); amyotrophic lateral sclerosis (18); autoimmune thyroid disease (16); prion disease (14); viral myocarditis (14); African trypanosomiasis (13); basal cell carcinoma (13); Fanconi anemia (11); herpes simplex infection (11); acute myeloid leukemia (10); alcoholism (10); arrhythmogenic right ventricular cardiomyopathy (10); human papillomavirus infection (10); pertussis (10); Salmonella Infections (10); small cell lung carcinoma (10); congestive heart failure (9); leishmaniasis (9); nicotine addiction (9); legionellosis (8); osteoporosis (8); Epstein-Barr virus infection (7); toxoplasmosis (7); dermatitis (6); scleroderma (6); chronic myeloid leukemia (5).
A further 272 diseases each share a sentence with PPARA in 5 papers or fewer.